DIAPH3 (diaphanous related formin 3)
Diseases named in the same sentence as DIAPH3 in open-access papers (continued):
Sharing a sentence is not in itself a finding about the gene and the disease.
osteosarcoma (1 paper, 2021). A usually aggressive malignant bone-forming mesenchymal neoplasm, predominantly affecting adolescents and young adults. "DIAPH3 protein is upregulated in osteosarcoma tissues, and its expression is significantly associated with tumor size, tumor stage, node metastasis, and distant metastasis." (PMID 35201449, 2021). "First, we found that DIAPH3 protein expression was significantly higher in osteosarcoma tissues than in normal bone tissues adjacent to cancer." (PMID 35201449, 2021). "The OD450 nm values of MG-63-shDIAPH3 and HOS-shDIAPH3 cells at 48 h and 72 h were significantly lower than those of MG-63-NC and HOS-NC cells, indicating that DIAPH3 knockdown suppressed the proliferation of osteosarcoma cells." (PMID 35201449, 2021). "The number of invaded MG-63-shDIAPH3 and HOS-shDIAPH3 cells in the Transwell Matrigel assay was significantly lower than that of migrated MG-63-NC or HOS-NC cells, indicating that DIAPH3 knockdown suppressed the invasion of osteosarcoma cells." (PMID 35201449, 2021). "DIAPH3 protein expression in osteosarcoma tissues and healthy bone tissues adjacent to cancer cells was examined by immunohistochemical staining." (PMID 35201449, 2021). "The percentage of MG-63-shDIAPH3 and HOS-shDIAPH3 cells in the G1 phase was significantly higher than that in MG-63-NC and HOS-NC cells, indicating that DIAPH3 knockdown induced cell cycle arrest in the G1 phase of osteosarcoma cells." (PMID 35201449, 2021). "In this study, we aimed to verify DIAPH3 expression in osteosarcoma tissues and cells, as well as the effect of DIAPH3 knockdown on cell proliferation and metastasis of osteosarcoma cell lines in vitro and in vivo." (PMID 35201449, 2021). "Functional in vitro experiments revealed that DIAPH3 knockdown suppressed cell proliferation and suppressed cell migration and invasion of osteosarcoma cell lines MG-63 and HOS." (PMID 35201449, 2021). "Next, we analyzed the correlation between DIAPH3 protein levels and the clinicopathological features of patients with osteosarcoma." (PMID 35201449, 2021). "These assays will help us to fully understand the function of DIAPH3 in osteosarcoma and identify an effective new target for osteosarcoma." (PMID 35201449, 2021). "Our study provides a potential target for pharmaceutical development and novel therapeutic strategies for the control of osteosarcoma proliferation and metastasis involving DIAPH3 inhibition." (PMID 35201449, 2021). "DIAPH3 expression predicts the clinical outcomes of osteosarcoma, and DIAPH3 knockdown can suppress cancer cell proliferation and metastasis." (PMID 35201449, 2021). "We sought to highlight the potential role of DIAPH3 as a critical biomarker for diagnosis and prognosis, as well as shed light on the function of DIAPH3 in regulating the proliferation and metastasis of osteosarcoma cell lines in vivo and in vitro." (PMID 35201449, 2021). "In this study, we aimed to evaluate the role of DIAPH3 in regulating the progression of osteosarcoma." (PMID 35201449, 2021). "In future studies, we will focus on the possible roles of DIAPH3 in osteosarcoma by regulating microtubule dynamics." (PMID 35201449, 2021). "Second, the regulatory mechanism underlying the involvement of DIAPH3 in the proliferation and metastasis of osteosarcoma has not been elucidated." (PMID 35201449, 2021). "This disrupted regulation of DIAPH3 suggests that DIAPH3 may play a role in tumorigenesis and the development of osteosarcoma." (PMID 35201449, 2021). "Moreover, DIAPH3 protein expression was higher in the osteosarcoma cell lines MG-63, HOS, U-2 OS, and Saos-2, than in osteoblast hFOB 1.19." (PMID 35201449, 2021). "Furthermore, functional in vitro and in vivo experiments indicated that DIAPH3 knockdown suppressed the proliferation and metastasis of osteosarcoma cells." (PMID 35201449, 2021). "Therefore, we predicted that DIAPH3 is involved in regulating the proliferation of osteosarcoma cells by controlling mitosis." (PMID 35201449, 2021).
osteosarcoma (continued). "In conclusion, DIAPH3 expression can predict the clinical outcome of osteosarcoma." (PMID 35201449, 2021). "This hypothesis is further supported by the correlation between DIAPH3 protein levels and the clinicopathological features of patients with osteosarcoma." (PMID 35201449, 2021). "In addition, DIAPH3 is involved in the proliferation and metastasis of osteosarcoma, and as such, DIAPH3 may be a potential therapeutic target for osteosarcoma." (PMID 35201449, 2021). "We hypothesized that DIAPH3 could be a new target for osteosarcoma, and factors that can suppress DIAPH3 expression or function may be effective for suppressing the tumorigenesis and development of osteosarcoma." (PMID 35201449, 2021). "Thus, we predicted that DIAPH3 might also be involved in the tumorigenesis of osteosarcoma." (PMID 35201449, 2021). "Therefore, it is rational to hypothesize that DIAPH3 is involved in osteosarcoma progression." (PMID 35201449, 2021). "Thus, DIAPH3 may be a new potential therapeutic target for osteosarcoma treatment." (PMID 35201449, 2021). "Moreover, our results suggest that DIAPH3 may play an oncogenic role in osteosarcoma progression." (PMID 35201449, 2021). "The early apoptotic rate was not significantly different between shDIAPH3 and the NC group (MG-63 and HOS) cells, indicating that DIAPH3 knockdown did not affect the apoptosis of osteosarcoma cells." (PMID 35201449, 2021). "To date, no study has investigated the expression and function of DIAPH3 in osteosarcoma." (PMID 35201449, 2021). "To date, there have been no reports on the function of DIAPH3 in osteosarcoma." (PMID 35201449, 2021).
sarcoma (1 paper, 2021). A usually aggressive malignant neoplasm of the soft tissue or bone. "Through bioinformatics analysis, we found that high DIAPH3 mRNA expression was correlated with a poorer OS rate and shorter DFS in patients with sarcoma." (PMID 35201449, 2021). "Bioinformatics analysis using the GEPIA dataset showed that high DIAPH3 mRNA expression was correlated with a poorer overall survival (OS) rate (P = 0.043) and shorter disease-free survival (DFS) in patients with sarcoma (P = 0.011)." (PMID 35201449, 2021).
skin cancer (1 paper, 2020). "To determine the translational relevance of our findings, we analyzed mDia2/DIAPH3 expression in human skin cancers and found a significant increase in mDia2/DIAPH3 mRNA levels in human BCC and cSCC samples as compared with normal skin." (PMID 32150356, 2020).
tumor (32 papers, 2008 to 2026). "Mammals possess three members of this protein family, diaphanous homolog 1 (DIAPH1), DIAPH2, and DIAPH3, which have been implicated in both normal cell physiology and tumor progression." (PMID 36589226, 2022). "Researches indicate that DIAPH3 deficiency has been linked to tumor invasion and metastasis in breast cancer and prostate cancer." (PMID 35538918, 2022). "Mammalian Diaphanous-related formin 2 (mDia2/DIAPH3/Drf3/Dia) assembles a dynamic F-actin cytoskeleton that underlies tumor cell migration and invasion." (PMID 29596520, 2018). "Our data suggest that DIAPH3 has a tumor-suppressor function and that its deficiency promotes aneuploidy and genome instability, accelerating tumorigenesis and leading to early onset of high-grade diffuse glioma with DNA damage, and resistance to ionizing radiation." (PMID 41872154, 2026). "In tumor cell migration, DIAPH3 was shown to be involved in several important processes, including the formation of extracellular vesicle, amoeboid mode invasion, and participation in tumor microenvironment (TME) with carcinoma‐associated fibroblasts." (PMID 35538918, 2022). "Furthermore, DIAPH3 expression was significantly associated with tumor size, tumor stage, node metastasis, and distant metastasis." (PMID 35201449, 2021). "They reported that in vitro, DIAPH3 knockdown in HeLa and SiHa cells suppressed proliferation, colony formation, and tumor growth in mice, accompanied by mTOR pathway inactivation." (PMID 41148856, 2025). "Silencing of Formin subfamily member DIAPH3 stimulates the formation and shedding of extracellular vesicles in PCa cells, hastening tumorigenesis and metastasis in vivo by modulating the tumor microenvironment." (PMID 39055653, 2024). "The enrichment analysis revealed that DIAPH3 was involved in tumor proliferation, invasion, and inflammation." (PMID 36750200, 2023). "The relationship between the expression of DIAPH3 and tumor immune checkpoints was analyzed by online analysis tools." (PMID 36750200, 2023). "As a result, we started by examining the relationship between DIAPH3 and tumor invasion and metastasis, with the goal of elucidating the mechanism by which it functions in CRC." (PMID 35538918, 2022). "The IHC data demonstrated that DIAPH1 and DIAPH3 expression were higher in tumor tissue when compared to adjacent normal tissue, and DIAPH2 was positively expressed in pancreatic acinar cells in adjacent normal tissue but not pancreatic ductal cells." (PMID 36589226, 2022). "Recently, proteomics has also shown us the novel phenotype of DIAPH3 in tumor regulation, including acting as a role for ubiquitin for regulating proteasome activity." (PMID 35538918, 2022). "In tumor cells, decreased DIAPH3 expression restricts actin extension and results in aberrant microtubules, resulting in dramatic alterations in cell shape and increased cell motility." (PMID 35538918, 2022). "Clarifying DIAPH3 mechanism can better explore the critical role of actin cytoskeleton in tumor development and metastasis of CRC." (PMID 35538918, 2022). "In accordance with our in vitro data, DIAPH3 knock down significantly alleviated tumour growth of Mia Paca‐2 cells and even prevents tumour of CFPAC‐1 cells from growing out." (PMID 33345387, 2021). "In prostate and breast cancer cells, DIAPH3 induces nuclear morphological instability and promotes malignant tumour phenotypes." (PMID 33345387, 2021). "Functional experiments demonstrated that DIAPH3 knockdown inhibited subcutaneous tumor growth and lung metastasis in vivo." (PMID 35201449, 2021). "In the group of tumor size larger than 3 cm, the expression level of DIAPH3 was significantly upregulated." (PMID 34659408, 2021). "And we confirmed that DIAPH3 expression was clearly related to tumor immune infiltrating cells (TIICs) by the analysis of CIBERSORT and TIMER databases." (PMID 34659408, 2021).
tumor (continued). "To further confirm it in a large cohort of patient samples, we analyzed the expression of DIAPH3 in CC in TCGA database, consisting of 305 tumor tissues and 3 normal tissues." (PMID 34659408, 2021). "This proinvasive role of DIAPH3 does not exclude its role as a genome safeguard since these mechanisms are implicated at different stages of tumor development." (PMID 38454929, 2024). "This level is likely underestimated given the significant tumor cell heterogeneity, and the fact that whereas the expression of DIAPH3 is restricted to proliferating cells, the methylation level was calculated as the percentage of methylated CpG in all tumor cells." (PMID 38454929, 2024). "This is exactly the opposite of the function of DIAPH3 in tumor cells." (PMID 35538918, 2022). "Notably, significant positive correlations between the expression of DIAPH3 and the infiltration of MDSCs were observed in all tumor types, except for THCA, UCS, GBM, and KICH in TCGA cohort." (PMID 36589226, 2022). "The depletion of DIAPH3 is also related to tumor progression and poor prognosis." (PMID 35538918, 2022). "However, there are contradicting findings in lung and pancreatic cancer, showing that DIAPH3 can promote tumor progression." (PMID 35538918, 2022). "To further investigate the functions of DIAPH3 on tumor development, we performed xenograft assays." (PMID 34659408, 2021). "Diaphanous homology 3 (DIAPH3) has different functions because of different tumour types." (PMID 34503532, 2021). "Therefore, we should adopt different DIAPH3‐targeting strategies to treat diseases according to its function and molecular mechanism of DIAPH3 in different tumours." (PMID 33345387, 2021). "The function of DIAPH3 in tumours differs depending on the tumour type." (PMID 33345387, 2021). "Taken together, our observations indicate DIAPH3 knock down could decrease tumour growth and TrxR1 expression in vivo." (PMID 33345387, 2021). "Furthermore, in mouse models, interference with DIAPH3 promotes the invasion and metastasis of tumour cells." (PMID 33345387, 2021). "While these studies focused upon the loss of mDia2 function and/or DIAPH3 expression, mDia2 agonism could impact tumor cells similarly, altering cells’ ability to drive cytoskeletal dynamics and execute downstream signaling through interacting partners." (PMID 30897774, 2019). "However, in tumor cells, DIAPH3 depletion leads to abnormal activity of the microtubule, which causes violent changes in morphology, enhances cell mobility, and promotes cell migration and those functions may not be mutually exclusive." (PMID 35538918, 2022). "Finally, nude mice xenograft model experimental results demonstrate DIAPH3 knock down could decrease tumour growth and TrxR1 expression and ROS levels in vivo." (PMID 33345387, 2021). "Therefore, we speculate that DIAPH3 may interact with different proteins in different tumours, thereby promoting or inhibiting tumour progression by different molecular mechanism." (PMID 33345387, 2021). "Similarly, DIAPH3 might play an important role in tumor metastasis through interactions between stromal fibroblasts and cancer cells." (PMID 33297976, 2020). "The expression levels of DIAPH1, DIAPH2, and DIAPH3 in PAAD tumor tissues were significantly higher than in normal tissues in the consensus databases of TCGA and GTEx." (PMID 36589226, 2022). "Notably, the expression levels of DIAPH1, DIAPH2, and DIAPH3 were significantly higher in PAAD tumor tissues than in normal tissues." (PMID 36589226, 2022). "Interestingly, we validated in vitro that DIAPH3 could promotes PDAC cells malignant phenotype via TrxR1‐mediated ROS levels and DIAPH3 knock down could decrease tumour growth and TrxR1 expression in vivo." (PMID 33345387, 2021). "Hence, tight regulation of DIAPH3, or mDia2 expression and/function as a mechanism to control cellular transformation and dissemination may not be employed solely by tumor cells, but by the TME cellular constituency as a whole." (PMID 29596520, 2018).
cancer (31 papers, 2012 to 2026). A tumor composed of atypical neoplastic, often pleomorphic cells that invade other tissues. "We performed a comparative transcriptomic analysis prior to the onset of tumors and identified changes in cancer gene signatures specifically in dcKO, suggesting that the loss of DIAPH3 hastens the tumorigenic process." (PMID 41872154, 2026). "As for nuclear instability, the nuclei of DIAPH3‐deficient cancer cells presented NE disruption, NM blebbing, cytosolic fragments containing nuclear material, and the release of extracellular vesicles with nuclear content." (PMID 39866838, 2025). "In turn, cancer-associated fibroblasts upregulate their own DIAPH3 levels to remodel the extracellular matrix and promote invasion." (PMID 34685534, 2021). "The dysregulated expression of Diaph3 has been observed in various cancer cells and is associated with cancer malignancy." (PMID 33187357, 2020). "Patients with strong DIAPH3 expression in fibroblasts were associated with poor OS (p = 0.003), and we successfully elucidated cancer stromal biomarker through combination framework of in vitro and in silico biomarker screening." (PMID 33297976, 2020). "DIAPH3 expression associates with immunotherapy response, validated in a pan-cancer cohort." (PMID 41545793, 2026). "Indeed, DIAPH3 regulates the function of mitochondria in dermal fibroblasts, promoting a protumorigenic cancer-associated fibroblasts phenotype." (PMID 36589226, 2022). "The enrichment of C6 analysis showed that the low expression of DIAPHs in PAAD of TCGA cohort was associated with genes downregulated by KRAS overexpression in cancer cell lines, whereas the high expression of DIAPH3 was associated with several oncogenes, such as E2F and EGFR." (PMID 36589226, 2022). "The role of DIAPH3 in tumorigenesis was investigated particularly in cancer cell migration and invasion." (PMID 38454929, 2024). "Each unit increase in genes DIAPH3, and PBK expression is associated with a 1.6-fold higher hazard of death, suggesting its potential role in cancer progression." (PMID 38914609, 2024). "An immunohistochemical experiment compared the expression and localization of DIAPH3 in cancer and normal cervical tissues." (PMID 36750200, 2023). "This latter observation is revealing because mDia2/DIAPH3 is key for proper mitochondrial positioning and activity in both normal and cancer-associated fibroblasts." (PMID 37240404, 2023). "It was observed that the expression of DIAPH3 in cancer tissue was higher than that in normal tissue, and it was in the cytoplasm." (PMID 36750200, 2023). "It was observed that the expression of DIAPH3 in cancer tissues was significantly higher than that in adjacent normal tissues." (PMID 36750200, 2023). "Diaphanous-related formin 3 (DIAPH3) has been identified to play crucial roles in many malignant tumors." (PMID 34659408, 2021). "Cancer cells in these tumors express high levels of activin A, and mDia2/DIAPH3‐positive cells were particularly abundant in the stroma." (PMID 32150356, 2020). "We analyzed fibroblasts in PDAC using our biomarker screening strategies through the cancer-stromal interaction model and found a novel prognostic marker in cancer fibroblasts: DIAPH3, actin-binding protein." (PMID 33297976, 2020). "Therefore, a more detailed analysis of the role of Diaph3 in cell division will contribute to the elucidation of the function of Diaph3 in microtubule stability and the mechanism underlying its effect on cancer malignancy, which may eventually lead to the application of Diaph3 as a targeted therapy." (PMID 33187357, 2020). "DIAPH3 down-regulation also sensitized cancer cells to growth suppression by MT-targeting chemotherapies." (PMID 26179371, 2015). "The expression of DIAPH3 in cancer tissue was higher than that in normal tissues." (PMID 36750200, 2023). "Research indicated that extravasated cancer cells could mediate the Rif/DIAPH3 pathway to initiate filopodium‐like protrusions (FLPs)." (PMID 35538918, 2022).